ACAA1 (acetyl-CoA acyltransferase 1)
Diseases named in the same sentence as ACAA1 in open-access papers (continued):
Sharing a sentence is not in itself a finding about the gene and the disease.
tumor (12 papers, 2019 to 2025). "ACAA1 was recently also implicated in regulating infiltration of T cell subtypes in the tumor stroma." (PMID 33194642, 2020). "Moreover, comprehensive xCell, ESTIMATE, and Immunophenoscore analyses underscored the positive association between ACAA1 and immune cell infiltration and the tumor immune effective microenvironment in NPC." (PMID 41277949, 2025). "Based on these associations, we hypothesise that high ACAA1 expression may indicate a tumour immune microenvironment more receptive to immune checkpoint blockade, positioning ACAA1 as a promising predictive biomarker for patient stratification." (PMID 41277949, 2025). "We therefore analyzed the correlation of ACAA1 expression and biomarkers of tumor burden mutation." (PMID 33194642, 2020). "Moreover, reduced ACAA1 expression is associated with lower overall survival in various types of cancer, indicating that ACAA1 acts as a tumor suppressor in a wide range of malignancies." (PMID 33194642, 2020). "•In summary, ACAA1 knockdown suppressed tumor growth by activating autophagy, which promoted the survival of KPC mice." (PMID 40848971, 2025). "These insights position ACAA1 as a potential therapeutic target for reprogramming anti-tumour immunity in NPC." (PMID 41277949, 2025). "ACAA1 knockdown inhibited tumor growth by triggering autophagy, which supported the survival of KPC mice." (PMID 40848971, 2025). "In conclusion, ACAA1 acts as a pivotal tumour suppressor in NPC through integrated effects on lipid metabolism, oxidative stress, cytoskeletal organisation, and immune modulation." (PMID 41277949, 2025). "Despite these associations, the functional role of ACAA1 in NPC, and its broader implications in tumour immunity, remains largely unexplored." (PMID 41277949, 2025). "After transplantation, the average tumor volume in the ACAA1 knockdown group decreased by 53%, 70%, and 7%, respectively, compared to the control group." (PMID 40848971, 2025). "Especially, a positive correlation between ACAA1 expression in tumor cells and six immune checkpoint-related genes, namely CD27, PDCD1, CD86, BTLA, TIGIT, and CD28, on immune cells within the tumor microenvironment." (PMID 41277949, 2025). "Emerging evidence has established ACAA1 as a tumour suppressor across multiple malignancies, with its under-expression consistently correlating with unfavourable clinical outcomes." (PMID 41277949, 2025). "Collectively, our findings highlight the potential of ACAA1 as a tumor - suppressor gene and suggest its possible involvement in the immune evasion mechanisms of NPC." (PMID 41277949, 2025). "Based on these findings, we propose a model in which ACAA1 modulates immune cell infiltration within the tumour microenvironment, thereby influencing NPC progression and survival." (PMID 41277949, 2025). "We found lower expression of ACAA1 in tumor tissue than in adjacent normal tissue in various cancers." (PMID 33194642, 2020). "Reduced expression of ACAA1 in the tumor cells also indicates lower level of mature T cells in tumor stroma." (PMID 33194642, 2020). "Collectively, these findings suggest that ACAA1 acts as a tumor suppressor in many types of cancers, possibly by altering the nutrient configuration and immune suppression." (PMID 33194642, 2020). "Copy number variation of ACAA1 also pointed to lower abundance of CD4+ in the tumor microenvironment." (PMID 33194642, 2020). "As TBX2 is the main marker of Th1 cells, these results indicate a positive relationship between ACAA1 and Th1 cell infiltration in the tumor stroma." (PMID 33194642, 2020). "Although the impact of ACAA1 mutation on cancer has not been thoroughly investigated yet, these results partially demonstrate that ACAA1 functionally recruits immune cells to the tumor microenvironment." (PMID 33194642, 2020).
tumor (continued). "Preliminary mechanistic insights suggest that this tumour-suppressive effect may involve ACAA1-mediated modulation of actin dynamics, including inhibition and spatial reorganisation of actin filaments." (PMID 41277949, 2025). "However, the main benefit of targeting ACAA1 is suppressing tumor growth by activating autophagy specifically in cancer cells, without harming normal cells." (PMID 40848971, 2025). "First, we aimed at elucidating whether ACAA1 had different expression patterns in tumor tissue and paired adjacent normal tissue." (PMID 33194642, 2020). "Next, we investigated whether ACAA1 expression was correlated to infiltration of immune cell in the tumor microenvironment, including B cells, CD8+ and CD4+ T cells, macrophages, neutrophils, and dendritic cells." (PMID 33194642, 2020). "ACAA1 showed lower mRNA levels in tumor tissues than in paired adjacent normal tissues." (PMID 33194642, 2020). "Thus, the expression pattern indicated that ACAA1 acts as a tumor suppressor in most types of cancers." (PMID 33194642, 2020). "Notably, there were 17 cases in which matched tumour and adjacent normal tissues were available, significantly consistent reduction of ACAA1 expression in tumour tissues was observed, reinforcing the tumour-specific nature of ACAA1 downregulation in NPC." (PMID 41277949, 2025). "In conclusion, exogenous ACAA1 expression inhibits the proliferation, migration, and invasion of NPC cells, highlighting its potential as a novel tumour suppressor." (PMID 41277949, 2025). "In the TCGA CRC dataset, three genes, ACAA1, CDH19, and SCGB2A1, were downregulated in tumor tissues, whereas the other three genes were overexpressed in tumor tissues." (PMID 35909904, 2022). "Here, similar to HSD17B4, ACAA1 was also found to be down-regulated and negatively correlated with MKI67 expression in NSCLC, indicating its anti-tumor potential." (PMID 32265992, 2020). "The results presented above indicate that CD4+ T cell infiltration correlated with ACAA1, and most subsets of CD4+ cells were reduced in the tumor stroma." (PMID 33194642, 2020). "Based on these scientific findings, we were motivated to analyze the potential role of ACAA1 in KRAS-mutant NSCLC and elucidate the correlation of ACAA1 with the immunosuppressive phenotype in the tumor microenvironment." (PMID 33194642, 2020). "Through Oncomine, Human Protein Atlas (HPA) and the Clinical Proteomic Tumor Analysis Consortium (CPTAC), three K-DEPGs (HSD17B4, ACAA1, and PXMP4) were confirmed to be down-regulated in NSCLC at both mRNA and protein level." (PMID 32265992, 2020). "The most important benefit of targeting ACAA1 is that it blocks tumor growth specifically in cancer cells without harming normal cell energy metabolism." (PMID 40848971, 2025). "Conversely, ACAA1 overexpression enhances fatty acid β-oxidation and decreases LD accumulation, underscoring its essential role in modulating lipid metabolism in NPC, and consequently influencing tumour cell survival and proliferation." (PMID 41277949, 2025). "Among them, ACAA1, GART, PDE9A, RPL3, TUBA1A, and TUBG1 gene products interact with several proteins known to be involved in the PRAD pathway and particularly important for apoptosis inhibition and tumor growth." (PMID 33712625, 2021). "Some adhesion molecules play an important role in tumor recurrence, metastasis, and invasion.(Okegawa, Pong, Li, & Hsieh, 2004) Based on the construction of PPI network and module analysis, ACAA1, ACADSB, ALDH6A1, AUH, HADH,and PCCA with high degree of connectivity were selected as hub genes." (PMID 30793530, 2019). "However, considering the differences in their prognostic effects, regulations, correlations with tumor purity and immune infiltrations effects between the two subtypes, further study is needed to investigate the specific functions of HSD17B4, ACAA1, and PXMP4 in LUSC and LUAD, respectively." (PMID 32265992, 2020).
tumor (continued). "HSD17B4, ACAA1, and PXMP4 were all strong expressed in lung (pneumocytes) while there was a negative to moderate expression of HSD17B4 and ACAA1 in the cytoplasm or membrane of LUSC and LUAD tumor cells." (PMID 32265992, 2020).
cancer (11 papers, 2020 to 2025). A tumor composed of atypical neoplastic, often pleomorphic cells that invade other tissues. "Furthermore, lower ACAA1 expression was shown to be associated the resistance of NSCLC cell lines to five different anti-cancer drugs including AZD0530, AZD6244, ZD-6474, Erlotinib and Lapatinib, providing new clues for NSCLC chemotherapy." (PMID 32265992, 2020). "ACAA1 has emerged as a significant player in immune-related pathological processes and cancer treatment responses." (PMID 41277949, 2025). "ACAA1 is an important regulator of fatty acid metabolism; presently, studies on ACAA1 have primarily focused on human metabolic diseases, tumors, and cancer." (PMID 34234807, 2021). "Cancers with higher ACAA1 expression level displayed higher overall survival, while those with reduced ACAA1 expression had worst outcomes." (PMID 33194642, 2020). "Here, we analyzed the differential expression of acetyl-CoA acyltransferase 1 (ACAA1) in various types of cancers using the TIMER database and validated the results in the NSCLC cell line H1944." (PMID 33194642, 2020). "In this study, to assess whether peroxisomal FAO is essential for cancer survival, ACAA1 was knocked down, as it is involved in the last step of β-oxidation that specifically targets peroxisomal FAO." (PMID 40848971, 2025). "Finally, we evaluated the prognostic value of ACAA1 in a wide range of cancers using the Kaplan-Meier Plotter Database." (PMID 33194642, 2020). "Therefore, downregulated ACAA1 expression may result in accumulation of fatty acids in cancer cells, consequently leading to DNA instability." (PMID 33194642, 2020). "Finally, we showed that ACAA1 is a predictive factor for survival in several cancer types." (PMID 33194642, 2020). "In cancer cells, however, knocking down CAC or ACAA1 decreases ATP production, which then activates AMPK." (PMID 40848971, 2025). "The expression of 24 FAM-related pathway genes was more active in para-cancer tissues than that in LUAD tissues, such as ACAA1, ACAT2, and ADH1B." (PMID 37920207, 2023). "Based on the expression profiles of 5 genes, PCA showed that normal and cancer samples were clearly separated, with COMP, ICA1, and PSMB1 contributing to PC1 and ACAA1 and with SCGB2A1 contributing to PC2." (PMID 35909904, 2022). "Expressional differences of HSD17B4, ACAA1, and PXMP4 between NSCLC cell lines with different anti-cancer drug sensitivity." (PMID 32265992, 2020). "We found that CDH19 and SCBB2A1 displayed negative signal intensity in the IHC stained cancer tissues, while ACAA1 showed moderate intensity in cancer tissues." (PMID 35909904, 2022). "In our study, we did not observe that KRAS mutation increased PD-L1 expression, nor a solid correlation of ACAA1 with PD-L1 expression in cancer cells using GEPIA (TCGA datasets)." (PMID 33194642, 2020). "As ACAA1 catalyzes fatty acid entry into the TCA cycle, we speculate that this phenotype could be due to nutrient competition between cancer cells and immune infiltrates." (PMID 33194642, 2020).
metabolic disease (2 papers, 2021 to 2024). A congenital disorder (due to inherited enzyme abnormality) or acquired (due to failure of a metabolically important organ) disorder resulting from an abnormal metabolic process. "Dysregulation of ACAA1 is associated with disturbances in lipid metabolism, implicating its role in various metabolic disorders." (PMID 38424613, 2024). "ACAA1 is an important regulatory gene involved in cell lipid metabolism and is a target of biotherapy for human metabolic diseases." (PMID 34234807, 2021).
ACAA1 also shares sentences with these, for which no sentence is quoted: Alzheimer disease (2 papers); liver cancer (2); male infertility (2); ovarian carcinoma (2); ampullary cancer (1); bladder cancer (1); celiac disease (1); colon cancer (1); COVID-19 (1); E. coli infection (1); eczema (1); enteropathy (1); head-neck cancer (1); infection (1); intestinal obstruction (1); kidney renal cancer (1); laryngeal carcinoma (1); male fertility (1); pancreatic adenocarcinoma (1); pancreatic ductal adenocarcinoma (1); paraganglioma (1); pheochromocytoma (1); prostate carcinoma (1); rectum adenocarcinoma (1); sarcoma (1); staphylococcus aureus infection (1); stomach cancer (1); thymoma (1); thyroid carcinoma (1); uterine corpus endometrial carcinoma (1).